HMGB1 (high mobility group box 1)
Diseases named in the same sentence as HMGB1 in open-access papers (continued):
Sharing a sentence is not in itself a finding about the gene and the disease.
colitis (continued). "Screening of DNA-bead constructs revealed that B2 beads, one linear form of DNA conjugated beads, bind HMGB1 with high affinity, capture HMGB1 ex vivo from endotoxin-stimulated RAW 264.7 cell supernatant and from feces of mice with colitis." (PMID 25127031, 2014). "In this study, we explored in vitro and in vivo the potential of DPG, a HMGB1 inhibitor, as an anti-inflammatory compound and showed that it strongly ameliorates DSS-induced colitis in mice." (PMID 23840500, 2013). "However, the concentrations of above inflammatory mediators were significantly decreased in colonic tissues of DSS-induced colitis mice compared to the DSS group after intervention with DPG, a HMGB1 specific inhibitor." (PMID 40689397, 2025). "Taking into account, the HMGB1 mediated inflammatory regulatory network revealed by bioinformatics analysis, this study carried out functional validation by constructing a Caco-2 cell inflammation model and a DSS-induced colitis model in mice." (PMID 40689397, 2025). "We observed a modest increase in HMGB1 and increased CD8+IFNγ+ cells during the colitis inflammatory process (DSS and UC) and in the early period after AOM administration, whereas CD8+IFNγ+ cells decreased and CD8+PDL1+ cells increased during carcinogenesis progression." (PMID 38999957, 2024). "In addition, the TNBS-induced C57BL/6 mice model of colitis presented decreased c-Casp3, BAX/BCL-2, c-Casp9, NLRP3, ASC, c-Casp1, GSDMD, IL-18, high mobility group box 1 (HMGB1), NF-κB, ERK, p38, and JNK." (PMID 37367886, 2023). "Furthermore, deletion of GSDME effectively reduces HMGB1 expression and release in colonic tissue models and alleviates inflammation in mouse models of DSS-induced colitis." (PMID 35677444, 2022). "DPG and G have presented antioxidant effects due to their negative modulation of Hmgb1 in the DSS-induced colitis mice model." (PMID 35456938, 2022). "IHC showed that HMGB1 was released to cytoplasm and extracellular sites in DSS-induced colitis." (PMID 33193406, 2020). "In this study, we found that genetic deletion of GSDME, an important executor protein of pyroptosis, could effectively decrease HMGB1 expression and release from colonic tissues in a DSS-induced colitis model." (PMID 33160389, 2020). "In mice with dextran sodium sulfate-induced colitis, lack of Hmgb1 in intestinal epithelial cells resulted in exacerbation of inflammation which was attributed to a defect in autophagy." (PMID 28275217, 2017). "B1 and B2 beads (20 μl) captured HMGB1 from the feces extracts from colitis mice whereas control beads did not." (PMID 25127031, 2014). "It is noteworthy that HMGB1 specific receptors, TLR4 and RAGE, are up-regulated in colon tissues in colitis environment, implicating the importance of identifying a treatment strategy that will effectively sequester and neutralize different isoforms of HMGB1 in IBD." (PMID 25127031, 2014). "Finally, HMGB1, abundantly present in the feces of mice with DSS-induced colitis, is strongly reduced by DPG." (PMID 23840500, 2013). "In DSS-induced colitis mouse model, HMGB1 upregulation accompanied by changes in TLR4, NF-κB, and GPX4 expression and ferroptosis-related genes upregulation, while inhibition of HMGB1 attenuated inflammation, restored barrier function, and reversed ferroptosis." (PMID 40689397, 2025). "Thus, although the timing of non-colitis and colitis carcinogenesis differs, almost parallel changes are observed, and HMGB1 plays an important role in both processes." (PMID 38999957, 2024).
depression (55 papers, 2014 to 2026). "previously elucidated the crucial role of CRP in mediating the association between trauma and depression, yet the potential mediating role of HMGB1 in this process remains inadequately explored." (PMID 40557138, 2025). "High mobility group box 1 protein (HMGB1)‐mediated inflammatory responses and associated neurofunctional impairments play a crucial role in the pathogenesis of depression." (PMID 40406924, 2025). "This study investigates the role of HMGB1 in anxiety and depression-like behaviors associated with the microglial Notch1/Hes-1 pathway in CRS mice." (PMID 39789446, 2025). "As a key mediator of neuroinflammation, HMGB1 has emerged as a promising candidate in adult depression, yet its diagnostic utility and mechanistic role in adolescents remain unexplored." (PMID 40557138, 2025). "Overall, our study demonstrates that HMGB1 serves as an efficient diagnostic biomarker for adolescent depression, with part of its effects mediated by childhood trauma, supporting a bio-psychosocial integrated intervention strategy." (PMID 40557138, 2025). "Several DAMPs have been implicated in depression, including high mobility group box-1 (HMGB-1), extracellular ATP, purine bases and metabolites, heat shock proteins (HSPs), S100 proteins, and galectin- 3 (Gal-3)." (PMID 37252156, 2023). "In a review on HMGB1 levels, an association with depression-like behaviours that are similar to motivational deficits was found." (PMID 37298365, 2023). "Elevated serum levels of HMGB1 were recently reported to be associated with depression after acute ischemic stroke." (PMID 37280213, 2023). "HMGB1 levels have been shown to be associated with depression-like behaviours that are similar to motivational deficits." (PMID 37298365, 2023). "Stress is an indirect cause of depression, which induces depression-like behaviors through the HMGB1/TLR4/NF-κB signaling pathway in the hippocampus." (PMID 36388178, 2022). "Previous studies demonstrated that depression-like behaviors caused by stress were dependent on HMGB1/TLR4/NF-κB and TNF-α/TNFR1/NF-κB signalling pathways in CUMS-exposed mice." (PMID 35386281, 2022). "Specific DAMPs such as S100 proteins, high-mobility group box 1 (HMGB1), heat shock proteins (HSPs), and ATP have been associated with the pathogenesis of mood disorders and are involved in stress-induced depression-like behaviors in mice." (PMID 33921690, 2021). "Thus, inhibition of HMGB1 is expected to be one of the therapeutic approaches for depression associated with neuroinflammation." (PMID 40461955, 2025). "The findings demonstrated that Lir might influence neuroinflammation and oxidative stress associated with microglia via the PI3K/Nrf2/HMGB1 signalling pathway and provides a potential approach for the treatment of depression." (PMID 40461955, 2025). "HMGB1 was selected as a potential predictor since it was independently linked to the severity of depressive symptoms and showed a significant difference between the depression and controls." (PMID 40557138, 2025). "Among these, ongoing studies in neurophysiology and neuropsychiatry have found that the activation of HMGB1 in microglial cells, leading to inflammatory responses, may be closely associated with the onset of depression." (PMID 40406924, 2025). "HMGB1 is another microglia-associated gene involved in depression." (PMID 37107654, 2023). "For this reason, one additional recommendation is to measure HMGB1 in patients taking NPSs, as its inappropriate levels may be responsible for an increased risk of depressive disorders." (PMID 37298365, 2023). "Persistent expression of HMGB1/RAGE in microglia increases susceptibility to depression." (PMID 36388178, 2022). "Studies of depression-like behavior induced by chronic unpredictable stress indicate that reduced hippocampal neurogenesis and increased depressive-like behaviors are associated with increased proinflammatory cytokines, increased HMGB1, and microglial RAGE expression." (PMID 31431637, 2019).
depression (continued). "In conclusion, this study positions HMGB1 at the intersection of neuroinflammation and psychosocial adversity in adolescent depression." (PMID 40557138, 2025). "Recent studies have identified High Mobility Group Box 1 (HMGB1) as a key mediator of neuroinflammation in depression." (PMID 40958792, 2025). "Serum HMGB1 levels are potential markers of depression, and childhood trauma partially mediates the relationship between HMGB1 and depressive symptoms severity." (PMID 40557138, 2025). "Subsequently, sustained HMGB-1 secretion from activated glia perpetuates neuroinflammation through cytokine feedback loops, a mechanism aligned with depression’s chronicity." (PMID 40557138, 2025). "In our study of adolescent depression, we found elevated levels of HMGB1, consistent with previous clinical studies in adult depression which reported significantly higher serum HMGB1 levels compared to controls." (PMID 40557138, 2025). "Previous studies demonstrated that in patients with depression comorbid with temporal lobe epilepsy, cytoplasmic translocation of HMGB1 in hippocampal CA region neurons was significantly increased." (PMID 40557138, 2025). "This study confirms that CRS mice exhibit symptoms of anxiety and depression, with elevated HMGB1 expression and stimulation of the Notch1/Hes-1 pathway in hippocampal microglia." (PMID 39789446, 2025). "Our study combined network pharmacology with in vivo and in vitro experiments to verify that Nrf2 and HMGB1 are important targets for Lir in the treatment of depression." (PMID 40461955, 2025). "HMGB1 appears to trigger neuroinflammation by activating the Notch1/Hes-1 pathway in hippocampal microglia, contributing to the emergence of anxiety and depression-like symptoms." (PMID 39789446, 2025). "Drawing on prior research, our investigation will focus on the effects of HMGB1 and the Notch1/Hes-1 pathway on anxiety and depression symptoms in CRS, as well as their mechanisms within hippocampal microglia." (PMID 39789446, 2025). "A clinical investigation has revealed that elevated serum HMGB1 levels correlate with the severity of depression in adult patients with depression." (PMID 40557138, 2025). "Correlation analysis showed that serum HMGB1 levels in depressive adolescents were positively correlated with 17-item Hamilton Depression Rating Scale (HAMD-17) scores and Childhood Trauma Questionnaire (CTQ) scores." (PMID 40557138, 2025). "The AUC, specificity, sensitivity and cut-off value of HMGB1 for identifying adolescent depression and controls was 0.9838, 97.5%, and 87.5%, 2117 pg/ml." (PMID 40557138, 2025). "Further analysis revealed that the AUC value for HMGB1 was higher in adolescent depression patients, potentially indicating more sensitive neuroinflammatory responses in this population." (PMID 40557138, 2025). "Serum HMGB1 levels can be objectively measured through standardized tests and exhibit a high correlation with the chronic inflammatory state of depression, demonstrating potential as an auxiliary indicator." (PMID 40557138, 2025). "While there is evidence supporting the potential role of ω-3 PUFAs in alleviating depression symptoms, studies specifically examining their effect on HMGB1, S100β, and NSE in individuals with depression are sparse." (PMID 39513898, 2024). "The infusion of HMGB1-neutralizing antibodies to the mPFC attenuated repeated social defeat stress-induced social avoidance, one of depression-related behaviors." (PMID 37443823, 2023). "In conclusion, we showed the roles of endogenous extracellular HMGB1 from mPFC neurons in regulating chronic stress-induced depression-related behavior." (PMID 37443823, 2023). "The prevalence of higher HMGB1 values in people with depression (MDD) has been shown to be higher than in healthy individuals." (PMID 37298365, 2023). "In terms of changes in serum HMGB1 concentrations, another fairly well-studied disease entity is depression." (PMID 37298365, 2023).
depression (continued). "In schizophrenia, symptoms of depression and anxiety are driven by immune and inflammatory pathways, wherein HMGB1 plays an important role." (PMID 37298365, 2023). "Treatment of mice with GZA, an HMGB1 inhibitor, prevented the activation of enzymes in the kynurenine (KP) pathway and the development of depression-like behaviours." (PMID 37298365, 2023). "It was reported that acute intracerebroventricular (i.c.v.)HMGB1 infusion induces depression-like behaviors under acute stress, such as prolonged immobility with tail suspension and decreased sucrose preference." (PMID 37443823, 2023). "It has been indicated that HMGB1 is one of the inflammatory factors involved in the mechanisms of depression." (PMID 37298365, 2023). "HMGB1-mediated microglia activation induces anxiety- and depression-like behaviours in mice with neuropathic pain." (PMID 37298365, 2023). "Collectively, these findings suggest that extracellular HMGB1 released from mPFC excitatory neurons promotes chronic stress-induced depression-related behaviors." (PMID 37443823, 2023). "Unexpectedly, this HMGB1 infusion attenuated social avoidance, one of the depression-related behaviors induced by repeated social defeat stress, compared with the vehicle infusion." (PMID 37443823, 2023). "It has also been reported that intracerebroventricular administration of HMGB1 induces depression‐like behaviors, such as prolonged immobility time in tail suspension test (TST) or forced swimming test (FST) and decreased sucrose preference." (PMID 37337402, 2023). "With these backgrounds, previous studies sought to examine the involvement of HMGB1 in depression-related behaviors." (PMID 37443823, 2023). "The results of a study on lipopolysaccharide (LPS)-induced depression showed that HMGB1 is involved in depression-like behaviours." (PMID 37298365, 2023). "HMGB1 is involved in depression-like behavior induced by lipopolysaccharide, and mice were used with human Recombinant HMGB1 (rHMGB1) to produce depression-like behavior." (PMID 35733802, 2022). "Collectively, the current study highlights the role of acupuncture in alleviating depressive behavior associated with stress-induced neuroinflammation mediated by HMGB1 in the CRS model of depression." (PMID 35733802, 2022). "The changes of the concentration of Iba-1 and HMGB1 in hippocampus were considered to be involved in the pathological process of depression." (PMID 35733802, 2022). "It is reported that stress can induce depression-like behaviours through the HMGB1/TLR4/NF-κB signalling pathway in the hippocampus and PFC." (PMID 35677442, 2022). "Clinical evidence showed that inflammatory mediators were elevated in patients with depressive disorder, such as HMGB1, IL‐1β, TNF‐α, CRP, IL‐6, and so on." (PMID 35089644, 2022). "In conclusion, inhibition of HMGB1 release or inhibition of HMGB1/TLR4/RAGE signaling pathway by HMGB1 inhibitors is beneficial for the treatment of depression." (PMID 36388178, 2022). "Several damage-associated molecular patterns (DAMPs) are associated with stress and depression, especially NLRP3 and HMGB1." (PMID 35677442, 2022). "Arctigenin exhibits significant antidepressant effects in rodent models of depression, attenuates microglial activation and neuroinflammation through HMGB1/TLR4/NF-κB and TNF-α/TNFR1/NF-κB signaling pathways, and inhibits IDO increase and decrease in 5-HT." (PMID 36388178, 2022). "In conclusion, the present study confirmed that BA possessed efficient antidepressant effects on depression, which was possibly related to the inhibition of HMGB1/TLR4/NF-κB pathways." (PMID 30658416, 2019). "In order to identify the intracellular mechanism responsible for the antidepressant effect of BA in CUMS induced depression, the protein expressions of BA on HMGB1, TLR4, p-NF-κB, NF-κB in the hippocampus were investigated." (PMID 30658416, 2019). "HMGB1 and netrin-1 are key factors involving in several neuroinflammatory conditions including depression." (PMID 31695615, 2019).
depression (continued). "A recent report indicates that elevated HMGB1 contributes to neuroinflammatory response in depression mouse model induced by CUMS." (PMID 30881312, 2019). "HMGB1, TLR4 receptors and/or neuroimmune activation are linked to many brain diseases including depression and neurodegeneration." (PMID 24551070, 2014). "Mediating effects of childhood trauma in HMGB1 levels and depression." (PMID 40557138, 2025). "Considering that adolescence is a peak period for depression onset and neuroinflammatory responses may be more pronounced at this stage, elevated HMGB1 levels in adolescent depression may be more evident." (PMID 40557138, 2025). "The HMGB1/NF‐κB/NLRP3 signaling pathway is involved in DACA's therapeutic effects on depression." (PMID 40406924, 2025). "Neuroinflammation, particularly High mobility group box 1 (HMGB1), a systemic inflammation mediator, is implicated in adult depression but not well-studied in adolescents." (PMID 40557138, 2025). "Our findings supported the inflammatory links between childhood trauma and psychopathology, indicating that HMGB1 exacerbates depression both directly through neuroinflammatory responses and indirectly by increasing individual susceptibility to the effects of childhood trauma." (PMID 40557138, 2025). "Preclinical studies have demonstrated that injecting recombinant HMGB1 (rHMGB1) into the lateral ventricles of neonatal mice can induce depression-like behaviors, while anti-HMGB1 antibody treatment suppresses microglial activation and ameliorate these behaviors." (PMID 40557138, 2025). "Abnormal HMGB1 expression is also closely related to anxiety and depression, suggesting that HMGB1-induced microglial activation may be a significant factor in the development of anxiety and depression in CRS patients." (PMID 39789446, 2025). "Given the potential link between HMGB1 activation and depression, we hypothesized that DACA might exert its antidepressant effects by targeting this pathway." (PMID 40406924, 2025). "HMGB1’s role in depression pathophysiology is underscored by its release kinetics." (PMID 40557138, 2025). "In addition to the well-known modulation by mental depression and pain, HMGB1 and other pro-and anti-inflammatory proteins participate in a network that contribute to the generation and regulation of fatigue." (PMID 37365509, 2023). "This type of stress could increase HMGB1 expression in the hippocampal microglia, and the infusion of HMGB1 into the mice hippocampus could also induce depression." (PMID 37107654, 2023). "Whether other TLR2/4 ligands, such as S100A8/A9, exert pro-depression-like actions together with HMGB1 in the mPFC remains to be examined." (PMID 37443823, 2023). "Given a higher proportion of stress-related mental illness, such as depression, in females over males, whether the behavioral role of HMGB1 in mPFC neurons found in this study is also applied to female mice warrants future investigation." (PMID 37443823, 2023). "Additionally, the administration of an anti‐HMGB1 antibody was reported to significantly suppress the prolonged immobility time in the FST which was observed in a mouse model of depression induced by neuropathic pain." (PMID 37337402, 2023). "Knockdown or inhibition of RAGE, a receptor to which HMGB1 can bind, may counteract the effects of chronic stress and behaviours that are characteristic of depression." (PMID 37298365, 2023). "Given that repeated social defeat stress may cause an extracellular release of endogenous HMGB1 proteins, we also examined whether the blockade of extracellular HMGB1 would affect chronic stress-induced depression-related behaviors." (PMID 37443823, 2023). "Despite substantial evidence implying a role for inflammatory signaling in prevalent neuropsychiatric disorders such as migraine and depression, how HMGB1 is released from healthy neurons and how inflammatory signaling is initiated in the absence of apparent cell injury are not well characterized." (PMID 38082296, 2023).